OR6K6 (olfactory receptor family 6 subfamily K member 6)
Description:
Odorant receptor.
Synonyms: OR1-21
Gene: Protein-coding gene on chromosome 1 (158,754,720 to 158,755,891, forward strand). Ensembl gene ENSG00000180433.
Subcellular location: Cell membrane
Pathways (Reactome):
Sensory Perception: Expression and translocation of olfactory receptors
Genetic constraint (gnomAD): Loss-of-function variants: 12 observed, 12.79 expected, observed/expected ratio (o/e) 0.94, 90% interval 0.6 to 1.51. The upper end of that interval is the gene's LOEUF score, 1.51, which puts it in group 6 of 6, group 1 being the genes least tolerant of losing a copy. Missense variants: 400 observed, 404.71 expected, observed/expected ratio (o/e) 0.99, 90% interval 0.91 to 1.07. Synonymous variants: 156 observed, 146.64 expected, observed/expected ratio (o/e) 1.06, 90% interval 0.93 to 1.22.
Homologues: Orthologues: chimpanzee OR6K6 (97% identical), macaque OR6K6 (92% identical), pig OR6K6 (87% identical), rabbit OR6K6 (85% identical), dog OR6K6 (82% identical), mouse Or6k6 (80% identical), rat Or6k6 (80% identical), guinea pig OR6K6 (78% identical). Paralogues in human: OR6K3 (63% identical), OR6K2 (60% identical), OR6N2 (49% identical), OR6N1 (49% identical), OR10K1 (40% identical), OR7C1 (40% identical), OR10R2 (39% identical), OR10Z1 (39% identical), OR1L1 (39% identical), OR1E1 (39% identical), OR2A1 (39% identical), OR2A42 (39% identical), and 116 more.
Diseases named in the same sentence as OR6K6 in open-access papers:
OR6K6 is named in the same sentence as 2 diseases in open-access papers, as found by Europe PMC text mining. Sharing a sentence is not in itself a finding about the gene and the disease. The quoted sentences say what the papers report.
cancer (1 paper, 2019). A tumor composed of atypical neoplastic, often pleomorphic cells that invade other tissues. "Interestingly, three out of the five non-synonymous mutated genes, Transmembrane Channel Like 3 (TMC3), Olfactory Receptor Family 6 Subfamily K Member 6 (OR6K6), and Unc-5 Family C-Terminal Like (UNC5CL), have been reported on in regard to an involvement with various cancer types." (PMID 31842489, 2019).
OR6K6 also shares sentences with these, for which no sentence is quoted: entropion (1 paper).